LGR5 (leucine rich repeat containing G protein-coupled receptor 5)
Diseases named in the same sentence as LGR5 in open-access papers (continued):
Sharing a sentence is not in itself a finding about the gene and the disease.
colitis (continued). "RNA probes were used to identify intestinal stem cells, marked by Lgr5, that renew the colon daily, as well as fetal-like precursors marked by Hopx, involved in the colitis response." (PMID 35223537, 2022). "To test the effects of BBR on ISCs, we induced colitis in Lgr5-CreERT-GFP; Rosa-tdTomato mice, which were treated with BBR." (PMID 36528592, 2022). "Our results showed that the mRNA levels of ISC maker genes, including Lgr5, Olfm4 and Ascl2, were significantly increased in the colon of colitis mice after L-fucose treatment." (PMID 36432480, 2022). "Immunofluorescence labeling for Lgr5 showed that the Lgr5+ cells were upregulated in the DSS-induced colitis group treated with BMP4." (PMID 34692671, 2021). "We further checked the colon epithelium proliferation and Lgr5+ ISC maintenance ability in DSS-induced colitis treated with BMP4 recombinant protein and antibody at 7 days." (PMID 34692671, 2021). "In conclusion, this study delineates the ability of Pectin and Tributyrin diets to alleviate colitis through microbiome and mucin restoration, Lgr5+ cell expansion, and reduced expression of proinflammatory markers." (PMID 35008767, 2021). "In the present study, our results showed that upregulated SMAD4 and BMP4 expression was related to a more rapid colon epithelium renewal and Lgr5+ ISC maintenance ability during the first 3 days of DSS induced experimental colitis in mice." (PMID 34692671, 2021). "In DSS-induced colitis, the number of Lgr5+ stem cells, the LC3II/I ratio and the level of p62 increase, which is aggravated by activating autophagy in Lgr5+ stem cells." (PMID 34588980, 2021). "The stimulatory effect of QCWZD on ISCs was further verified by a higher percentage of Lgr5-positive ISCs in colitis mice with QCWZD treatment compared to those receiving sterile water alone." (PMID 34557102, 2021). "Related to this, Zhao and coworkers recently reported that the deletion or silencing of non-muscle myosin II in murine IEC protects against experimental colitis and promotes survival of Lgr5+ stem cells and growth of IEC organoids." (PMID 33525555, 2021). "Our data showed that intestinal epithelium proliferation and Lgr5+ ISCs were increased during the first 3 days of colitis." (PMID 34692671, 2021). "They showed that Lgr5 expression is gradually increased as tumors developed with repeated colitis and reported all dysplastic lesions and cancers showed high Lgr5 expression." (PMID 33541282, 2021). "This study proposes that a Pectin diet, probably through the generation of SCFAs, protects the colonic epithelium in colitis-infected mice by reducing hyperplasia and restoring gut homeostasis via lgr5+ stem cell expansion." (PMID 35008767, 2021). "Since the intestinal epithelium proliferation and Lgr5+ stem cells were essential for maintaining the epithelium turnover upon DSS colitis, we investigated at days 0, 3, 5, and 7, respectively." (PMID 34692671, 2021). "We investigated the rate of colon regeneration in DSS-induced colitis with rapamycin intraperitoneally administered to Lgr5-GFP mice." (PMID 33106485, 2020). "Delayed mucosal regeneration with reduced expression of Lgr5 and C-myc has been observed previously in a model of colitis in STAT6−/− mice." (PMID 31877961, 2019). "Blebbistatin protects Lgr5+ stem cells against colitis-induced epithelium injury in gastrointestinal tissues through the Myh9-Rac1-PAK1-Akt pathway and induces cell migration through myosin-II-related matrix stretch and recoil." (PMID 32116554, 2019). "GELNs cause significant induction of Lgr5 intestinal stem cells through the Wnt/β-catenin pathway, protecting mice from DSS-induced colitis." (PMID 31689969, 2019). "Our results further exhibited a stronger staining of lysozyme and LGR-5 in the gut epithelial crypt of patients with colitis too." (PMID 26687459, 2015).
colitis (continued). "In conclusion, our results indicate that NGR1 alleviates DSS-induced colitis in mice by promoting the restoration of Lgr5+ stem cells and epithelial integrity, and this effect is mediated, at least partially, through the activation of the Wnt/β-Catenin signaling pathway." (PMID 38491161, 2024). "Similarly, immunofluorescence for the ISC marker Lgr5 revealed that L-fucose significantly promoted the ISC regeneration in DSS-induced colitis compared to the DSS group (p = 0.0275)." (PMID 36432480, 2022). "Likewise, real-time quantitative PCR showed that the mRNA expression of the ISC marker genes Lgr5, Olfm4 and Ascl2 was increased in the L-fucose-treated colitis mice." (PMID 36432480, 2022). "Furthermore, deletion of NHE8 both causes ulcerative colitis-like disease and promotes the occurrence of colitis-related cancers in mice by increasing expression of leucine-rich repeat containing G protein-coupled receptor 5 (Lgr5)." (PMID 34778915, 2021). "Thus, in order to confirm the function of BMP4 on intestinal epithelium, we dynamically detected the intestinal epithelium proliferation and Lgr5+ ISCs in mice with DSS-induced colitis." (PMID 34692671, 2021). "Administration of QCWZD expedited ISCs proliferation, as evidenced by significant compensated the expressions of stem cell markers such as Lgr5 and achaete-scute like-2 (Ascl2) in colon of colitis mice in the present of QCWZD when compared to mice in DSS group." (PMID 34557102, 2021). "This hypothesis is supported by other studies showing that Lgr5+ stem cells are highly sensitive to epithelial injury induced by radiation or colitis." (PMID 33541282, 2021). "BMP4 recombinant protein treatment could preserve Lgr5+ ISCs, colon epithelium turnover, and could even alleviate the symptoms of colitis in experimental mice by targeting ID3." (PMID 34692671, 2021). "We find that Lgr5+ cells are lost during colitis, confirming previous reports in different models." (PMID 31554819, 2019). "To test this hypothesis, we induced colitis in CRS-treated Lgr5-creERT2; NR3C1fl/fl mice." (PMID 40360481, 2025). "Indeed, Lgr5+ stem cells are dispensable for epithelial regeneration after experimental colitis." (PMID 39461590, 2024). "Thus, even in tumors arising through more conventional molecular pathways in the setting of colitis, LGR5 expression might be affected by ongoing inflammation and repeated mucosal injury." (PMID 33541282, 2021). "LGR5+ expression drops dramatically during the acute stages of colitis but increases dramatically during regeneration; other studies confirm that LGR5+ expressing stem cells may be very sensitive to intestinal injury but nonetheless crucial to crypt regeneration." (PMID 30386335, 2018). "In DSS-induced colitis, VillinCre;Dclk1f/f mice demonstrated exacerbated injury including higher clinical colitis scores, increased epithelial barrier permeability, higher levels of pro-inflammatory cytokines and chemokines, decreased levels of Lgr5, and dysregulated Wnt/b-Catenin pathway genes." (PMID 26285154, 2015). "Our data demonstrated that mucosal regeneration is closely correlated with the number of LGR5-expressed epithelial cells with a positive correlation of Lgr5 and Sox9, following the chronic phase of DSS-mediated colitis." (PMID 41596428, 2026). "Collectively, these data suggest that Mettl3 depletion in Lgr5+ stem cells inhibits the self-renewal and differentiation and promotes DSS-induced colitis." (PMID 39762134, 2025). "Orthogonal support for stem cell stress was provided by analyzing N1RA/RA; N2RA/RA; Lgr5-EGFP-IRES-creERT2 mice, which lost weight rapidly from day 4 relative to N1+/+; N2+/+; Lgr5-EGFP-IRES-creERT2 when exposed to 2% DSS to induce colitis." (PMID 39666740, 2024). "In the progression from colitis to colorectal cancer, targeted inhibition of MUC1-C plays a crucial role in blocking LGR5+ intestinal stem cells (ISCs), Myc, and pluripotency factors signaling pathways, slowing down the worsening of colitis." (PMID 38361923, 2024).
colitis (continued). "PSTi8 treatment in males preserved the Lgr5+ cell population while depleting HOPX+ and LY6A+ cells in colitis." (PMID 39684467, 2024). "We next examined the mRNA expression of markers for fast-(Lgr5) and slow-cycling (Hopx) stem cells by in situ hybridization at distinct stages of DSS-induced colitis." (PMID 31708126, 2019). "Since Rspo3 is a major determinant of Lgr5+ stem cell identity and essential for maintaining the proliferative compartment upon DSS colitis, we asked how DSS affects the stem cell pool." (PMID 31554819, 2019). "Single Lgr5 + ISC-derived colonoids transplantation accelerated the recovery of epithelial barrier function and reversal of inflammation in the DSS colitis model." (PMID 28588586, 2017). "Lgr5, a marker of intestinal stem cells, was significantly (p < 0.05 and p < 0.01, respectively) increased in the mice treated with both IFN-γ-primed and naïve cAMSCs compared to in the DSS-induced colitis mice." (PMID 39595338, 2024). "It maintains the function of Lgr5+ ISC, and resists DSS‐induced colitis." (PMID 39465140, 2024). "At this stage of recovery, Bmal1+/+ controls no longer have any DSS-induced lesions present (colitis is resolved), but Hopx and Lgr5 expression persists in the Bmal1-/- mutant lesions." (PMID 35223537, 2022). "Sca-1 has also been shown to be expressed on epithelia during active colitis with crypt disruption where Lgr5 expression was absent and the Hippo pathway effectors YAP/TAZ were active." (PMID 34665221, 2021). "Moreover, they found that Clu+ single cell cluster 2 (SSC2) cells were able to reconstitute the damaged Lgr5+ ISC niche to revival crypt cell populations (revSCs), in both acute and chronic dextran sodium sulfate (DSS) colitis mouse models." (PMID 33282867, 2020). "We demonstrate that Hopx+ CARSCs arise during the reparative stage of colitis, preceded by an injury phase when Lgr5/Hopx double negative atrophic crypts are prevalent near areas of ulcerations." (PMID 31708126, 2019). "The expression level of cycling stem cell marker Lgr5 was decreased more than 50%, and the expression level of Bmi1 decreased about 20% in Dclk1f/f mice after DSS treatment, suggesting a decrease in both stem cell populations following DSS-induced colitis." (PMID 26285154, 2015). "Our data suggest that the lesions of the TZ with Lgr5 expression might be remodeled to severe colitis, but they did not have the potential for squamous cell carcinoma under the present study conditions." (PMID 39684417, 2024). "Interestingly, the cell state in the TNFα-treated wt organoids was similar to Mex3a positive cells, Lgr5 positive cells, and colitis cells, but not correlated with label-retaining cells (LRC) or other differentiated cells." (PMID 37845228, 2023). "Importantly, a prior work utilizing Lgr5-Cre-driven GPBAR1 conditional knockout mice revealed that intestinal stem cells exhibited impaired self-renewal, reduced differentiation capacity, and delayed post-colitis regeneration, accompanied by disrupted YAP/SRC signaling pathway activation." (PMID 41228488, 2025). "Finally, in Abx-generated pseudo-germ-free mice, HQD failed to up-regulate AhR signaling or to promote Lgr5+ ISC differentiation, and it no longer offered protection against DSS-induced colitis." (PMID 41530817, 2026).
breast cancer (51 papers, 2015 to 2025). A primary or metastatic malignant neoplasm involving the breast. "High stromal LGR5 expression was observed in 21 (33%) cases and showed associations with younger age (P = 0.026), family history of breast cancer (P = 0.011), and the presence of residual tumor (P = 0.006)." (PMID 35778589, 2022). "This study showed that high levels of LGR5 expression were significantly associated with tumor size ≥ 2 cm and LN metastasis in breast cancer patients, and that poorly differentiated tumors exhibited a trend toward higher LGR5 expression (p = 0.072)." (PMID 29471794, 2018). "We next investigated associations between LGR5 expression, breast cancer recurrence, and patient mortality." (PMID 29471794, 2018). "However, a variety of cancers, including breast cancer, are associated with the modulation of L-type VGCCs, and the AM stem/progenitor cell marker LGR5 was significantly upregulated in AM, which is similar to the results of a previous study." (PMID 36057617, 2022). "However, little is known about the associations between LGR5 expression and breast cancer clinicopathological features." (PMID 29471794, 2018). "We also examined whether β-catenin was differentially associated with LGR5 as a function of breast cancer molecular subtype." (PMID 29471794, 2018). "High LGR5 expression was also associated with reduced RFS, indicating that LGR5 may represent a promising prognostic marker for breast cancer patients." (PMID 29471794, 2018). "Moreover, the CSC-associated marker leucine-rich repeat-containing G protein-coupled receptor 5 (LGR5) has been previously shown to promote breast cancer progression and CSC maintenance, in part through activation of Wnt/β-catenin signaling." (PMID 29471794, 2018). "LGR5 promoted cisplatin resistance of breast cancer cells (MCF-7) through PKA (Protein Kinase A) and LGR5-KD inhibited docetaxel drug resistance." (PMID 39821694, 2025). "LGR5 enhances cell movement, tumor development, and the epithelial-mesenchymal transition in breast cancer cells." (PMID 40210723, 2025). "The aim of this study was to investigate Znhit1 and HIF-2α gene expression in breast cancer tissues as well as their relation to CSCs markers LGR5, ALDH1A1 and β-catenin in tissue and serum of BC patients." (PMID 35978075, 2022). "In a study by Shi and colleagues, the function of miR-340 and LGR5 in breast cancer and their effect on drug resistance were discussed." (PMID 33718760, 2021). "As a result of this study, in addition to the introduction of the LGR5 gene as a downstream target for the mir-340, it has also been confirmed that the miR-340 and LGR5 genes have a suppressive and oncogenic role in breast cancer, respectively." (PMID 33718760, 2021). "The G-protein receptor 5 (LGR5) is overexpressed in a part of breast cancers and activates beta-catenin signaling in these tumor cells via protein kinase A." (PMID 32210163, 2020). "Intriguingly, lineage tracing demonstrated that Lgr5+ cell progeny generated the bulk of hyperplastic mammary tumors." (PMID 32522170, 2020). "In LGR5-overexpressing breast cancers, Wnt signaling induces cancer progression and drug resistance." (PMID 32210163, 2020). "In breast cancers, the members of the Wnt signaling family are rarely mutated: APC (1.3%), CTNNB1 (0.2%), AXIN1 (0.4%), LRP6 (0.7%), LGR5 (0.6%), TCF7L2 (0.3%), and FBXW7 (1.5%)." (PMID 32210163, 2020). "LGR5 is overexpressed in various breast cancer subtypes and particularly in TNBCs; in these last tumors, a correlation between LGR5 expression and nuclear beta-catenin staining was observed." (PMID 32210163, 2020). "Lgr5 has been demonstrated to promote cancer cell mobility, tumor formation, and epithelial-mesenchymal transition in breast cancer cells via activation of Wnt/β-catenin signaling." (PMID 31358061, 2019). "Additional markers and siRNA profiling showed high expression of ALDH and LGR5 in agreement with the stem cell characteristics of breast cancer cells." (PMID 31105876, 2019).
breast cancer (continued). "Recently, Tspan8 was identified as a biomarker for a subset of deeply quiescent mammary stem cells (Lgr5+Tspan8hi), whose transcriptome resembled claudin‐low breast carcinoma 18, thus indicating a potential role in breast cancer." (PMID 30982971, 2019). "Using the Zhao breast microarray dataset, we observed that LGR5 expression was lower in normal breast compared to breast cancer tissue (17 invasive ductal carcinomas and 20 lobular carcinomas)." (PMID 29471794, 2018). "Subsequently, we constructed a tissue microarray (TMA) using specimens from 126 breast cancer patients, and performed semi-quantitative immunohistochemistry (IHC) for LGR5 and β-catenin." (PMID 29471794, 2018). "Leucine-rich repeat-containing G protein-coupled receptor 5 (LGR5) has been identified as a CSC-associated Wnt-regulated target gene, but its clinical significance in the context of breast cancer remains elusive." (PMID 29471794, 2018). "Nevertheless, taken together, our study indicates that the development of drugs that inhibit LGR5 expression will be an important strategy for breast cancer treatment." (PMID 29471794, 2018). "We further investigated the associations between LGR5 and β-catenin expression level and 5-year relapse-free survival (RFS) in breast cancer patients." (PMID 29471794, 2018). "We next used specimens obtained from 126 breast cancer patients to investigate the clinical importance of LGR5 expression." (PMID 29471794, 2018). "Overall, our clinical data showed that breast cancer patients with high levels of tumor LGR5 expression have shorter RFS compared to those with low levels of tumor LGR5 expression." (PMID 29471794, 2018). "In contrast, a recent study reported the upregulation of Lgr5 expression in MMTV-Wnt1 mammary tumor cells and in human breast cancer cell lines when incubated with Wnt3a." (PMID 27420097, 2016). "LGR5-KD significantly reduced the metastasis of breast cancer (MDA-MB231) cells in vivo." (PMID 39821694, 2025). "Similarly, unipotent Krt5 and Lgr5 expressing cells in these studies were also described to form mammary tumors (mostly adenomyoepitheliomas) upon Pik3caH1047R expression, composed of both epithelial cell types revealed by lineage tracing." (PMID 40676433, 2025). "LGR5 promoted breast cancer cells to undergo EMT through the WNT/β-catenin signaling pathway." (PMID 39821694, 2025). "Beyond the Wnt/β-catenin pathway, a well-established regulator of cancer stemness, we analyzed the expression of core pluripotency factors, including Nanog, KLF4, LGR5, and Sox2, which are critical for maintaining self-renewal, tumorigenicity, and therapy resistance in breast cancer stem cells." (PMID 41347072, 2025). "A recent investigation found that high LGR5 protein levels in estrogen-negative (ER-) breast cancer were associated with reduced recurrence-free survival and OS, but interestingly, high LGR5 levels in ER + breast cancers were associated with better outcomes." (PMID 39821694, 2025). "In addition, this miR inhibited cell proliferation in multiple systems, such as in CRC (by decreasing Lgr5 expression) or in mammary tumor cells both in vitro and in vivo." (PMID 35216292, 2022). "Overexpression of LGR5 is significantly correlated with advanced clinical stage and metastatic status of breast cancer, indicating that LGR5 may be a promising prognostic marker for patients with breast cancer." (PMID 36288272, 2022). "Lgr5, also known as G protein-coupled receptor 49, was first identified by Aaron J. W. Dr Hsueh’s team, and the overexpression of Lgr5 has been reported in a variety of cancers, such as breast cancer." (PMID 36185219, 2022). "We previously utilized RNAscope and showed that high LGR5 expression might be a poor prognostic factor in breast cancer." (PMID 33676447, 2021).